SNHG3 (small nucleolar RNA host gene 3)
Diseases named in the same sentence as SNHG3 in open-access papers (continued):
Sharing a sentence is not in itself a finding about the gene and the disease.
lung adenocarcinoma (7 papers, 2018 to 2022). A carcinoma that arises from the lung and is characterized by the presence of malignant glandular epithelial cells. "To predict the functions of SNHG3 in lung adenocarcinoma, we constructed a gene coexpression network according to Pearson correlation coefficients using the TCGA database." (PMID 30154938, 2018). "We found that SNHG3 promoted proliferation, cell cycle, and suppressed cell apoptosis of lung adenocarcinoma, suggesting that SNHG3 acted as an oncogene in lung adenocarcinoma." (PMID 30154938, 2018). "We also performed functional experiments to explore the roles of SNHG3 in lung adenocarcinoma cells." (PMID 30154938, 2018). "To investigate the specific roles of SNHG3 in lung adenocarcinoma cells, we also detected the cellular localization of SNHG3 in A549 and H1299 cells by separating cells into the nucleus and cytoplasmic fractions." (PMID 30154938, 2018). "We also overexpressed SNHG3 in lung adenocarcinoma cells and investigated its effect on the cell proliferation and apoptosis." (PMID 30154938, 2018). "Of note, SNHG3 showed the most significance between lung adenocarcinoma samples and adjacent normal tissues." (PMID 30154938, 2018). "To explore the function of SNHG3 on lung adenocarcinoma, we first detected the cellular localization of SNHG3 in A549 and H1299 cells." (PMID 30154938, 2018). "In conclusion, we demonstrated that SNHG3 expression was upregulated in lung adenocarcinoma and overexpression of SNHG3 promoted SNHG3 cell proliferation." (PMID 30154938, 2018). "To further explore the molecular function of SNHG3 in lung adenocarcinoma, we overexpressed SNHG3 and found that SNHG3 promoted lung adenocarcinoma cell proliferation, cell cycle, and suppressed cell apoptosis." (PMID 30154938, 2018). "Aiming to evaluate the functions of SNHG3 in lung adenocarcinoma, we transfected A549 and H1299 cells with the expression plasmid pcDNA 3.1(+)-SNHG3." (PMID 30154938, 2018). "We found that upregulation of SNHG3 in A549 and H1299 cells inhibited early and late apoptosis in lung adenocarcinoma." (PMID 30154938, 2018). "To characterize the role of SNHG3 in regulating cell proliferation in lung adenocarcinoma cell lines, we performed a CCK-8 assay in A549 and H1299 cells." (PMID 30154938, 2018). "Taken together, these results suggested that SNHG3 acted as an oncogene in lung adenocarcinoma." (PMID 30154938, 2018). "In this study, we demonstrated that SNHG3 was upregulated in lung adenocarcinoma." (PMID 30154938, 2018). "Moreover, we constructed a SNHG3-mediated competing endogenous RNA network to explore the molecular mechanisms involved in SNHG3 regulating lung adenocarcinoma progression." (PMID 30154938, 2018). "Here, we observed that SNHG3 was significantly upregulated in lung adenocarcinoma." (PMID 30154938, 2018). "In our research, we focused on studying the molecular function of SNHG3 in lung adenocarcinoma." (PMID 30154938, 2018). "We also overexpressed SNHG3 in lung adenocarcinoma cells and found that enhanced SNHG3 expression could significantly promote lung adenocarcinoma cell proliferation, cell cycle, and suppressed cell apoptosis." (PMID 30154938, 2018). "Then, we studied the role of SNHG3 in apoptosis in lung adenocarcinoma." (PMID 30154938, 2018). "Therefore, SNHG3 may be a potential new target for the treatment and prognosis of lung adenocarcinoma." (PMID 33292213, 2020). "However, the molecular function of SNHG3 in lung adenocarcinoma remains unclear." (PMID 30154938, 2018). "Therefore, SNHG3 might serve as a therapeutic target in lung adenocarcinoma." (PMID 30154938, 2018).
laryngeal carcinoma (6 papers, 2020 to 2022). Carcinoma that arises from the laryngeal epithelium. "SNHG3 can modulate the cell growth and migration of laryngeal carcinoma by modulating miR‐384/WEE1 pathway." (PMID 32248648, 2020). "For example, SNHG3 could promote laryngeal carcinoma proliferation and migration by binding miR-384." (PMID 33596916, 2021).
non-small cell lung carcinoma (6 papers, 2020 to 2024). A group of at least three distinct histological types of lung cancer, including non-small cell squamous cell carcinoma, adenocarcinoma, and large cell carcinoma. "Investigating SNHG3 in non-small cell lung cancer (NSCLC) through in vitro experiments and bioinformatics analyses, the study revealed its significant upregulation in NSCLC." (PMID 39349640, 2024). "Silencing SNHG3 is a controller of the miR-216a/ZEB1 axis in non-small cell lung cancer (NSCLC) to constrain cancer malignant progression." (PMID 35123415, 2022).
acute myeloid leukemia (4 papers, 2020 to 2022). Acute myeloid leukemia (AML) is a group of neoplasms arising from precursor cells committed to the myeloid cell-line differentiation. "In acute myeloid leukemia, SNHG3 expression was found to have strong association with platelet count and white blood cell count." (PMID 32802874, 2020). "For example, in acute myeloid leukemia, high expression of SNHG3 enhances cell proliferation and inhibits cell apoptosis by acting as a miRNA sponge for miR-758-3p to enhance serglycin (SRGN) levels." (PMID 35030969, 2022). "In other words, SNHG3 promotes the growth of acute myeloid leukemia cells by regulating the miR-758-3p/SRGN axis, providing a new therapeutic direction for the treatment of AML." (PMID 33292213, 2020). "SNHG3 was shown to be up-regulated in acute myeloid leukemia (AML) samples and cells, and knockdown of SNHG3 could inhibit leukemia cell proliferation and induce cell apoptosis." (PMID 33922442, 2021).
cholangiocarcinoma (4 papers, 2020 to 2024). A carcinoma that arises from the intrahepatic biliary tree (intrahepatic cholangiocarcinoma) or from the junction, or adjacent to the junction, of the right and left hepatic ducts (hilar cholangiocarcinoma). "In a separate study, researchers elucidated SNHG3's role in cholangiocarcinoma (CCA)." (PMID 39349640, 2024).
clear cell renal cell carcinoma (4 papers, 2020 to 2025). "SNHG3 activates the progression of clear cell renal cell carcinoma via regulating the expression of miR‐139‐5p and as a result to up‐regulate TOP2A expression." (PMID 32248648, 2020). "Additionally, in clear cell renal cell carcinoma (ccRCC), SNHG3 influences proliferation and metastasis via the SNHG3/miR-139-5p/TOP2A axis." (PMID 39349640, 2024).
Alzheimer disease (3 papers, 2019 to 2024). A progressive, neurodegenerative disease characterized by loss of function and death of nerve cells in several areas of the brain leading to loss of cognitive function such as memory and language. "SNHG3 was firstly implicated in Alzheimer's disease (AD) and its up-regulation might be an indicator of a wider dysregulation of translational machinery and ribosome biogenesis during AD neurodegeneration." (PMID 32284745, 2020).
breast tumor (3 papers, 2020 to 2022). "Western blot showed that increasing of miR-330 and SNHG3 knockdown significantly decreased the protein expression of PKM in breast tumor cells, while silencing of miR-330 and overexpression of SNHG3 markedly increased the PKM level in MD-MBA-453 cells." (PMID 31956955, 2020). "The results indicated that knockdown of CAF-secreted exosomal the decrease of SNHG3 expression inhibited cell growth and glycolysis metabolism of breast tumor cells in vitro and in vivo." (PMID 31956955, 2020). "Orthotopical xenograft of breast tumor experiments was performed to determine the function of SNHG3 in vivo." (PMID 31956955, 2020). "Our study demonstrated that SNHG3/miR-330 signaling axis regulated the proliferation and metabolism of breast tumor cells through modulating PKM at the post-transcription level, providing potential therapeutic targets for inhibiting PKM in cancer treatment." (PMID 31956955, 2020). "Knockdown of CAF-secreted exosomal SNHG3 could inhibit the growth of breast tumor cells Mechanistically, SNHG3 could serve as a molecular sponge of miR-330 to regulate the expression of PKM in breast tumor cells." (PMID 31956955, 2020). "However, the functional roles of CAF-secreted SNHG3 in breast tumor remained unknown." (PMID 31956955, 2020). "As we have demonstrated the exosomes secreted from CAFs could promote proliferation and reprogram metabolism of breast tumor cells, we further examined whether the effect is dependent on CAF-secreted exosomal lncRNA SNHG3." (PMID 31956955, 2020). "SNHG3 functions as a miR-330-5p sponge to positively regulate PKM expression, inhibit mitochondrial oxidative phosphorylation, increase glycolysis carboxylation, and enhance breast tumor cell proliferation." (PMID 31956955, 2020).
esophageal cancer (3 papers, 2020 to 2025). A primary or metastatic malignant neoplasm involving the esophagus. "After that, we have found that SNHG3 was highly expressed and miR-186-5p was lowly expressed in esophageal cancer in vitro." (PMID 33596916, 2021). "Moreover, we have found aberrant high expression of SNHG3 and low expression of miR-186-5p in esophageal cancer both in vitro and in vivo." (PMID 33596916, 2021). "Decreased levels of COL4A1, DEK, GINS1, HPCAL1, KIF4A and RBMX predicted longer survival in esophageal cancer patients, while overexpression of IGFL1P1, LRRC57A-AS1, SNHG3, ULK3 and ZFYVE19 correlated with longer survival." (PMID 41326355, 2025). "In contrast, IGFL1P1, LRRC57A-AS1, SNHG3, ULK3 and ZFYVE19 showed poor expression in esophageal cancer tissues but high expression in the combined treatment group." (PMID 41326355, 2025). "However, the specific role of SNHG3 in esophageal cancer was not reported yet." (PMID 33596916, 2021).
oral squamous cell carcinoma (3 papers, 2022 to 2024). "In Oral Diseases, research elucidated molecular mechanisms in oral squamous cell carcinoma (OSCC), particularly focusing on HOXB8 regulation and its interaction with SNHG3/miR-2682-5p." (PMID 39349640, 2024). "Similarly, in oral squamous cell carcinoma (OSCC), SNHG3 influences nuclear transcription factor Y subunit gamma, promoting cell proliferation and migration and suggesting its potential as a novel biomarker." (PMID 39349640, 2024).
papillary thyroid carcinoma (3 papers, 2020 to 2025). "Notably, low SNHG3 expression was significantly associated with worse clinical outcomes for papillary thyroid carcinoma patients, particularly in terms of recurrence free survival (RFS)." (PMID 41042421, 2025). "The results were further corroborated by RT-PCR analysis, which demonstrated a more than 1.5-fold decrease in SNHG3 expression in papillary thyroid carcinoma tissues (38/62, 61.3%) relative to matched normal thyroid tissues." (PMID 41042421, 2025). "SNHG3 is linked to lymph node/distant metastases and Tumor Node Metastasis (TNM) stage in cancers like bladder, breast, colorectal, gastric, liver, ovarian, and papillary thyroid carcinoma." (PMID 41042421, 2025). "However, in papillary thyroid carcinoma, there are contrary reports of SNHG3 expression." (PMID 41042421, 2025). "Initial investigations into SNHG3 expression using the GEPIA platform and GEO datasets revealed reduced expression in papillary thyroid carcinoma tissues when being contrasted to normal thyroid tissues." (PMID 41042421, 2025). "The authors did not analyze the discrepancies in the expression and role of SNHG3 between papillary thyroid carcinoma and various other cancers." (PMID 41042421, 2025).
thyroid cancer (3 papers, 2021 to 2025). "Functional experiments further confirmed that SNHG3 knockdown significantly enhanced the proliferation, invasion, and metastatic capacity of thyroid cancer cells." (PMID 41234719, 2025). "SNHG3 and SNHG5 show relatively low expression in thyroid cancer and possess certain inhibitory effects, closely linked to their roles in autophagy regulation (the SNHG5–RBM47/USP21–FOXO3 axis) and modulation of AKT/mTOR/MAPK signaling pathways." (PMID 41234719, 2025). "Further molecular mechanism studies revealed that SNHG3 knockdown upregulates key molecules in the AKT/mTOR and MAPK/ERK signaling pathways (p-AKT, p-mTOR, and p-ERK), thereby accelerating thyroid cancer progression." (PMID 41234719, 2025). "In thyroid carcinoma, certain SNHG family members (e.g., SNHG7, SNHG15, SNHG12, SNHG14) have been reported as oncogenes, while others (e.g., SNHG3, SNHG5) may function as tumor suppressors—a discrepancy warranting further investigation." (PMID 41234719, 2025).
cervical cancer (2 papers, 2022 to 2025). A primary or metastatic malignant neoplasm involving the cervix. "SNHG3 knockdown by ASOs has been demonstrated to inhibit migration and invasion in HeLa cervical cancer cells." (PMID 41042421, 2025). "In cervical cancer, SNHG3 promotes the proliferation, migration, and invasion of cervical cancer cells in vitro, and facilitates cervical cancer growth in vivo." (PMID 35406713, 2022).
intrahepatic cholangiocarcinoma (2 papers, 2020 to 2022). A carcinoma that arises from the intrahepatic bile duct epithelium in any site of the intrahepatic biliary tree. "A previous study proposed that SNHG3 could be used as an independent prognostic biomarker of intrahepatic cholangiocarcinoma." (PMID 35778697, 2022).
prostate adenocarcinoma (2 papers, 2020 to 2022). "To reveal the clinical significance of SNHG3 in PC, we first analyzed the expression pattern of SNHG3 in The Cancer Genome Atlas-Prostate Adenocarcinoma (TCGA-PRAD) database." (PMID 35030969, 2022).
aortic valve calcification (1 paper, 2025). "Recently, the role of specific lncRNAs, including SNHG3, LINC01013, and lncTSI, in aortic valve calcification has been reported." (PMID 40937116, 2025).
autoimmune disease (1 paper, 2025). A disorder resulting from loss of function or tissue destruction of an organ or multiple organs, arising from humoral or cellular immune responses of the individual to their own tissue constituents. "LINC00963, SNHG15, and SNHG3 are lncRNAs that have garnered attention for their roles in cancer and autoimmune disorders." (PMID 39969652, 2025). "Notably, the up-regulation of lncRNAs such as LINC00963, SNHG15, and SNHG3 underscores their significant involvement in inflammatory cascades and highlights their potential utility as biomarkers or therapeutic targets in autoimmune diseases." (PMID 39969652, 2025).
bone metastasis (1 paper, 2022). Transfer of a neoplasm from its primary site to bones. "Since bone metastasis is a significant prognostic factor for PC patients, we investigated the role of SNHG3 in PC bone metastasis." (PMID 35030969, 2022). "Moreover, increased expression of SNHG3 predicted poor overall survival (OS) and bone metastasis-free survival (BMFS) in PC patients." (PMID 35030969, 2022). "Notably, high expression of SNHG3 was prevalent in PC with bone metastasis (PC/BM) relative to PC without bone metastasis (PC/nBM)." (PMID 35030969, 2022).
Hepatic fibrosis (1 paper, 2024). The presence of excessive fibrous connective tissue in the liver. "In future, the effect of Snhg3 on hepatic fibrosis in mice need to be elucidated by prolonged high-fat diet feeding or adopting methionine- and choline deficient diet (MCD) feeding." (PMID 39436790, 2024).
Hepatic steatosis (1 paper, 2024). Steatosis is a term used to denote lipid accumulation within hepatocytes. "Furthermore, hepatocyte-specific Snhg3 deficiency decreased body and liver weight, alleviated hepatic steatosis and promoted hepatic fatty acid metabolism in DIO mice, whereas overexpression induced the opposite effect." (PMID 39436790, 2024). "To this end, we tested the effect of T0070907, a selective PPARγ antagonist, on Snhg3-induced hepatic steatosis in mice." (PMID 39436790, 2024). "To clarify the molecular mechanism of Snhg3 in hepatic steatosis, we investigated the hepatic differentially expressed genes (DEGs) using RNA-Seq." (PMID 39436790, 2024). "Experiments conducted using in vivo and in vitro models indicated that Snhg3 was involved in fatty acid metabolism and hepatic steatosis." (PMID 39436790, 2024). "The administration of PPARγ antagonist T0070907 improved Snhg3-aggravated hepatic steatosis." (PMID 39436790, 2024). "In this study, lncRNA-Snhg3 is downregulated in DIO mice and hepatocyte-specific Snhg3 deficiency improved hepatic steatosis and insulin resistance, while overexpression aggravated hepatic steatosis and insulin resistance in mice." (PMID 39436790, 2024). "To further clarify whether Snhg3-induced H3K27me3 decrease is involved in hepatic steatosis, we examined the H3K27me3 enrichment in the liver of Snhg3-HKO mice using the CUT&Tag assay and detected 10915 peaks." (PMID 39436790, 2024). "Hepatocyte-specific Snhg3 knockout alleviates hepatic steatosis in DIO mice." (PMID 39436790, 2024). "Furthermore, inhibition of PPARγ with T0070907 alleviated Snhg3- and SND1-induced Cd36 and Cidea/c increase and improved Snhg3-aggravated hepatic steatosis." (PMID 39436790, 2024). "Snhg3 promotes hepatic steatosis through regulating chromatin remodeling." (PMID 39436790, 2024). "Moreover, administration of PPARγ antagonist T0070907 mitigated the hepatic Cd36 and Cidea/c increase and improved Snhg3-induced hepatic steatosis." (PMID 39436790, 2024). "Collectively, these results suggested that PPARγ-mediated Snhg3-induced hepatic steatosis." (PMID 39436790, 2024). "Hepatocyte-specific Snhg3 overexpression aggravates hepatic steatosis in DIO mice." (PMID 39436790, 2024). "Also, Snhg3-HKI mice exhibited severe hepatic steatosis and higher serum ALT and AST levels." (PMID 39436790, 2024). "This study reveals a new signaling pathway, Snhg3/SND1/H3K27me3/PPARγ, responsible for hepatic steatosis and provides evidence of lncRNA-mediated epigenetics in the pathophysiology of MASLD." (PMID 39436790, 2024). "The Snhg3-HKO mice had a decrease in liver weight and the ratio of liver weight/body weight, and improved hepatic steatosis, including decreasing lipid accumulations and the ballooning degeneration of liver cells." (PMID 39436790, 2024). "(G) Model of how Snhg3 and SND1 interacting and influencing chromatin remodeling via H3K27me3, and promoting PPARγ expression thereby resulting in hepatic steatosis." (PMID 39436790, 2024).
ischemic stroke (1 paper, 2024). A stroke disorder caused by obstruction of blood flow to the brain, due to thrombotic (local blood clot formation) or embolic (due to a blood clot or other material traveling from another site) event. "They found that in contrast to miR-485, the expression of lncRNA SNHG3 was upregulated in ischemic stroke models, leading to increased levels of Beclin-1 and LC3-II/LC3-I ratio." (PMID 39021183, 2024).
lymph node metastasis (1 paper, 2020). "Ten studies provided available data for analyses between SNHG3 expression and clinical parameters, including age, gender, clinical stage, tumor size, lymph node metastasis, distant metastasis, and differentiation." (PMID 32802874, 2020). "Additionally, patients with high SNHG3 expression tended to have more advanced clinical stage, higher histological grade, earlier distant metastasis, and earlier lymph node metastasis." (PMID 32802874, 2020). "Additionally, patients with high SNHG3 expression were more prone to have more advanced clinical stage, higher histological grade, earlier distant metastasis, and earlier lymph node metastasis." (PMID 32802874, 2020). "This study demonstrated that overexpressed SNHG3 was significantly associated with poor survival, including OS, DFS, and RFS and worse clinical outcomes, including clinical stage, histological grade, distant metastasis, and lymph node metastasis in human cancers." (PMID 32802874, 2020).